RNU6-1011P (RNA, U6 small nuclear 1011, pseudogene)
Gene: Small nuclear RNA gene on chromosome 8 (103,384,961 to 103,385,067, forward strand). Ensembl gene ENSG00000207399.
Homologues: Orthologues: chimpanzee U6 (99% identical), rabbit U6 (94% identical), macaque U6 (93% identical). Paralogues in human: RNU6-12P (94% identical), RNU6-13P (94% identical), RNU6-26P (94% identical), RNU6-31P (94% identical), RNU6-32P (94% identical), RNU6-33P (94% identical), RNU6-38P (94% identical), RNU6-1 (93% identical), RNU6-1060P (93% identical), RNU6-15P (93% identical), RNU6-17P (93% identical), RNU6-18P (93% identical), and 1285 more.